EPO (erythropoietin)
Diseases named in the same sentence as EPO in open-access papers (continued):
Sharing a sentence is not in itself a finding about the gene and the disease.
anemia (continued). "The dysfunction of erythropoietin (EPO) production because of declining renal function is the major cause of anaemia in patients with chronic renal failure." (PMID 17216497, 2007). "Recombinant human erythropoietin (r-HuEPO) has become the standard of care in treating anaemia associated with chronic renal failure (CRF) in adults as well as in children." (PMID 17216497, 2007). "The primary cause of anaemia in CKD patients is insufficient synthesis of erythropoietin by the damaged kidneys." (PMID 17999759, 2007). "Anemia in HIV-infected adults has the characteristics of the "anemia of chronic disease" and is associated with an impaired erythropoietin (EPO) response to anemia and failure to mobilize iron from liver stores." (PMID 16390553, 2006). "We conclude that HIV-related anemia is associated with attenuation in the EPO response to anemia in early infancy, but that the EPO response is normalized by 6 months." (PMID 16390553, 2006). "Recombinant human EPO has been used since the 80's in the treatment of anemia associated to end-stage renal disease." (PMID 15910687, 2005). "Diminished arterial oxygen content associated with anemia or hypoxia is the major stimulus for EPO production and usually produces an exponential increase." (PMID 15987387, 2005). "Hemoglobin and EPO values were compared with those of 20 (5 male, 15 female; mean age 60 years, range 24–84 years) control patients with iron deficiency anemia." (PMID 15987387, 2005). "Patients with cancer are frequently anaemic, with contributing factors including chemotherapy and the anaemia of chronic disease, with endogenous erythropoietin deficiency, relative erythropoietin resistance, and shortened red cell survival." (PMID 12177793, 2002). "In 20 patients with cisplatin-associated anaemia (haemoglobin less than 90 gl-1), recombinant human erythropoietin was administered subcutaneously three times a week on an outpatient basis." (PMID 8427776, 1993). "Carcinoma NT in CBA mice causes a progressive anaemia which can be overcome by daily injections of recombinant human erythropoietin (rHuEpo)." (PMID 8398699, 1993). "In the management of geriatric anemia, it is essential to consider organ-specific aging processes associated with underlying inflammatory conditions, with particular attention to impaired erythropoietin production that occurs independently of eGFR decline." (PMID 41625058, 2026). "Such an approach could help clinicians better differentiate between anemia due to reduced erythropoietin production, iron deficiency, or increased erythrocyte destruction." (PMID 40643488, 2025). "Impaired renal erythropoietin (EPO) production in CKD patients significantly elevates anemia risk." (PMID 41561116, 2025). "In MM, anemia results from bone marrow infiltration, relative erythropoietin (EPO) deficiency, chemotherapy-induced myelosuppression, and nutritional deficiencies (iron, B12, and folate), which increase Hb variability and reduce its reliability as a cardiac risk marker." (PMID 40969263, 2025). "Second, optimization of preoperative anemia via iron or erythropoietin supplementation if appropriate and identification of risk factors for transfusion reactions and transfusion necessity are critical to reduce transfusion requirements, particularly in young, otherwise healthy patients." (PMID 41141016, 2025). "Anemia of chronic disease in SLE is also associated with reduced erythropoietin activity, partly due to diminished production and the presence of anti-EPO antibodies, which may correlate with disease activity and complement consumption." (PMID 41156173, 2025). "For MF-associated anemia, erythropoietin, steroids, danazol, lenalidomide (in case of chromosome 5q deletion), momelotinib, or luspatercept may be given alone or in combination with ruxolitinib and other compounds." (PMID 40094998, 2025).
anemia (continued). "Therefore, elderly patients with anemia are likely to be deficient in iron and EPO, which are essential for the anemia-improving effects of SGLT2 inhibitors, and the treatment-induced increase in hemoglobin tends to be smaller than that in nonelderly patients." (PMID 40620843, 2025). "The proposed mechanism that could explain this coexistence is that stunting could cause anemia by decreasing the erythropoietin production." (PMID 40426817, 2025). "Fourth, although HbA1c levels are typically measured using standard methods, certain conditions, such as iron deficiency anemia, erythropoietin administration, and splenectomy, may influence measurement accuracy." (PMID 40672815, 2025). "Decreased erythropoietin production, thrombocytopathy, impaired nutrient intake due to hyporexia/anorexia, shortened red cell lifespan, and gastrointestinal bleeding due to uremic gastroenteritis are reported to be among the causes of anemia." (PMID 40612148, 2025). "Age-related physiological changes, such as reduced erythropoietin production by the kidneys or decreased red cell production in the bone marrow, may contribute to the higher risk of anemia." (PMID 41383345, 2025). "In the first study, 505 patients with either preoperative anemia or iron deficiency were randomized to receive either 20 mg/kg ferric carboxymaltose, 40,000 U subcutaneous erythropoietin alfa, 1 mg subcutaneous B12, and 5 mg oral folic acid or placebo on the day before surgery." (PMID 41303295, 2025). "Notably, while ADTKD-UMOD patients rarely develop early anemia, the current case presented with early anemia despite normal EPO levels, suggesting a potential renin deficiency-related mechanism similar to that in ADTKD-REN." (PMID 41480152, 2025). "This study aimed to examine the associations among ERFE, hepcidin, EPO, and hemoglobin, and to determine whether these markers independently relate to anemia severity in CKD." (PMID 41227183, 2025). "In clinical practice, recombinant human erythropoietin (rHuEPO) is used to treat anemia associated with chronic kidney disease, chemotherapy-induced anemia in cancer patients, and anemia in patients with human immunodeficiency virus/acquired immune deficiency syndrome (HIV/AIDS)." (PMID 40191193, 2025). "Beyond oncology, EPO is extensively utilized in the treatment of anemia associated with CKD." (PMID 41012526, 2025). "Insufficient renal EPO production is the principal causative factor of anemia in patients with CKD." (PMID 40364122, 2025). "Telomere shortening may be associated with anemia and erythropoietin resistance in patients with CKD undergoing hemodialysis." (PMID 40244253, 2025). "In contrast, anemia in the elderly is well known to be associated with malnutrition, such as iron deficiency, and/or chronic disease and inflammation, with inhibited production and action of EPO and increased hepcidin." (PMID 40620843, 2025). "Furthermore, animal studies have demonstrated that protein deficiency can induce anemia by inhibiting effective erythropoiesis through reduced protein synthesis in erythroid cells and decreased erythropoietin production, even when iron stores are sufficient." (PMID 39931366, 2025). "Erythropoietin (EPO) deficiency contributes to the development of anemia in CKD." (PMID 40364122, 2025). "The presence of coexisting disease increased the occurrence of preoperative anemia due to the fact that, coexisting diseases can suppress the bone marrow function and decrease activations of erythropoietin steam cells and malnutrition which leads to deficiency of iron and some important vitamins." (PMID 41233925, 2025). "The reduction of these variables in cats with CKD may be associated with anemia due to the reduction in erythropoietin, a decrease in the lifespan of red blood cells due to uremia, or even functional iron deficiency." (PMID 40182825, 2025).
anemia (continued). "Therefore, an insufficient number of hypoxia-inducible factor (HIF)-sensitive REPCs in response to hypoxic stimuli causes an EPO decrease and erythropoiesis, leading to the development of anemia." (PMID 38610814, 2024). "And third, chronic inflammation, by interfering with iron and erythropoietin metabolisms, causes anemia which may participate in frailty." (PMID 38481213, 2024). "Notably, anemia is linked to a relative shortage of erythropoietin as well as to the sufficiency of dialysis treatment." (PMID 39839624, 2024). "Several factors have been implicated in the earlier onset of anemia in diabetic patients, such as glucotoxicity, systemic inflammation, inhibition of erythropoietin release, damage to the renal interstitium, sympathetic denervation of the kidneys, and altered iron metabolism." (PMID 39541418, 2024). "Anemia due to erythropoietin deficit and blood loss during hemodialysis is also frequent." (PMID 38534719, 2024). "While the roles of erythropoietin (EPO), hypoxia-inducible factor prolyl hydroxylase inhibitors, iron ions, inflammation, and infection have been well established, Cu deficiency is an often overlooked cause of anemia in this population." (PMID 39336525, 2024). "The anaemia is associated with impaired erythropoietin responses, despite being elevated." (PMID 39267208, 2024). "Clinically, the risk of bone loss should be considered when using EPO to treat anemia." (PMID 39278948, 2024). "Also, the frequent administration of recombinant erythropoietin (rhuEPO) for the correction of end-stage renal disease-induced anemia is considered to be one of the causes of LT apoptosis, especially CD4+ LTs." (PMID 38921685, 2024). "AKI may contribute to anemia through different mechanisms, such as reduced life span of RBCs, increased risk of bleeding, and reduced production of erythropoietin (EPO), although the association between anemia and AKI progression is controversial." (PMID 38787184, 2024). "Since CKD patients often require EPO therapy to manage anemia, high L-FABP levels can indicate underlying kidney damage that may contribute to ESA resistance." (PMID 39518373, 2024). "While the relationship between anemia and HF outcomes also involves inflammatory stress and insufficient EPO production, any of these mechanisms could underlie anemia and RDW elevation in HF." (PMID 38434056, 2024). "In addition, anemia in ESKD can be caused by decreased erythropoietin production and an increased rate of erythrocyte clearance as well." (PMID 38731843, 2024). "Interestingly, anemia-related factors, including iron deficiency and erythropoietin, have been shown to increase FGF23 production." (PMID 37752381, 2024). "By boosting red blood cell production, EPO therapy may reduce the severity and frequency of complications associated with anaemia, such as pain crises, organ damage due to reduced oxygenation, and the need for blood transfusions." (PMID 38463100, 2024). "In other words, low-dose roxadustat combined with erythropoietin therapy not only improves anemia and relieves ESA resistance but also reduces the risk associated with adverse events of higher doses of roxadustat, which is worthy of clinical reference and application in ESA-hyporesponsive patients." (PMID 39010898, 2024). "The administration of recombinant human erythropoietin (rhEPO) was associated with lower proportions of anemia, abnormal ferritin, and abnormal iron levels (63.27%, 26.53%, and 61.22%, respectively) compared to those not receiving rhEPO (79.66%, 35.59%, and 69.49%, respectively)." (PMID 38792868, 2024). "Renal anemia is an almost inevitable complication of CKD patients and is defined as anemia resulting from the impaired production of erythropoietin (EPO) in the kidney; a deficiency in EPO reduces the hematopoietic stimulation of the bone marrow, resulting in anemia." (PMID 38338786, 2024).
anemia (continued). "Uremic toxins like IS, which accumulate in the blood instead of being filtered and excreted by the kidneys, lead to a deficiency in EPO production by renal interstitial fibroblasts (peritubular cells of the kidney), resulting in a decrease in red blood cell production and anemia." (PMID 38612557, 2024). "This aligns with existing literature emphasizing the increased susceptibility to anemia in CKD patients due to factors such as erythropoietin deficiency, iron metabolism disturbances, and chronic inflammation induced by renal dysfunction leading to alterations in ferritin, hepcidin, and transferrin." (PMID 39109107, 2024). "Therefore, the administration of intravenous iron in association with erythropoietin has become a common clinical practice to correct anemia in patients on dialysis." (PMID 39121099, 2024). "Falsely low HbA1c values in CKD patients may be caused by erythropoietin insufficiency, anaemia, and erythrocyte fragmentation." (PMID 39231139, 2024). "This leads to the hypothesis that anemia correction before the procedure (with iron and/or erythropoietin) may limit the risk of a post-procedural worsening of neurocognitive function." (PMID 38682100, 2024). "Damaged fibroblast may cause a significant reduction in the local production of EPO, thus contributing to the development of anemia." (PMID 38787184, 2024). "Although the etiology of CKD is multifaceted, EPO deficiency may be the primary contributor to anemia in CKD patients." (PMID 39390059, 2024). "Moreover, parallel hypermethylation in the 5′-enhancer and promoter of the EPO gene causes suppression of EPO in myofibroblasts and consequent anemia in CKD." (PMID 38790642, 2024). "In addition to renal failure, EPO has also been investigated for its potential to treat anemia associated with cancer." (PMID 39355466, 2024). "In patients with sepsis, RBC levels are negatively associated with CD45+ CEC frequency, suggesting that anemia may lead to CEC expansion through the EPO pathway." (PMID 39474425, 2024). "In addition, erythropoietin deficiency and hyporesponsiveness can lead to anaemia in diabetic patients with CKD." (PMID 38562414, 2024). "It is established that hypothyroidism causes anemia, which may be due to bone marrow suppression, a reduced level of erythropoietin, comorbidities, or a concomitant deficiency of hematinics." (PMID 39830579, 2024). "Although low EPO levels have specifically been associated with unexplained anemia in the elderly population, the exact cause of the inadequate EPO response is still unknown." (PMID 38610814, 2024). "Furthermore, distinct autonomic dysfunction states have beendescribed in patients with CAN, including erythropoietin deficiency, anaemia, andearly dysregulation of erythropoietin production." (PMID 39139439, 2024). "To examine the impact of prolonged hypoxia on inflammation, we used a genetically engineered mouse model of systemic hypoxia, inherited super-anaemic mice (ISAM), which exhibit severe anaemia caused by erythropoietin insufficiency and consequent tissue hypoxia 19,20." (PMID 38822028, 2024). "The last type of anemia might be caused by reduced erythropoietin (EPO) activity, progressive EPO resistance of bone marrow erythroid progenitors, and the chronic subclinical pro-inflammatory state." (PMID 38610814, 2024). "A central role in erythropoietin resistance has been associated with erythropoiesis inhibition driven by cytokines and hepcidin, a peptide produced by inflammatory cells and involved in the anemia of inflammatory chronic disease." (PMID 39130834, 2024). "These patients may have anemia, mostly caused by decreased erythropoietin secretion and other factors, and increased susceptibility to bleeding because of aggravated hemolysis." (PMID 38420005, 2024). "Testosterone deficiency was also a cause of anemia and reduced responsiveness to erythropoietin." (PMID 39253627, 2024).
anemia (continued). "Similar to anemia, thrombocytopenia in preterm infants may result from a marked deficiency in erythropoietin production due to their immature kidneys, with the severity increasing as the GA at birth decreases." (PMID 39457121, 2024). "Erythropoietin (EPO) inadequacy, abnormal iron metabolism, systemic inflammation, blunted bone marrow response, and nutritional deficiency, along with a reduced erythrocyte lifetime, are the major causes of anemia of CKD (ACKD)." (PMID 39155928, 2024). "Recent evidence has proposed that FGF23 could be involved in the association with indirect markers of inflammation, such as functional iron deficiency (particularly TSAT), anemia with an increased need of EPO, and death." (PMID 38999530, 2024). "However, EPO unresponsiveness in several patients is common, suggesting that undefined causes affect anemia." (PMID 37511089, 2023). "Anti-erythropoietin (anti-EPO) antibody production may be implicated in the pathogenesis of Plasmodium falciparum malaria-related anaemia in pregnancy." (PMID 36989322, 2023). "In addition to iron supplementation, treatments with the aim to increase EPO levels and, thus, correct anemia in CKD and the association with FGF23 have been investigated." (PMID 36831276, 2023). "The urinary loss of transferrin, erythropoietin, transcobalamin, ceruloplasmin, iron, and trace elements may lead to anemia." (PMID 37606426, 2023). "The reduction of endogenous erythropoietin, impaired iron absorption, increased hepcidin levels, increased levels of uremic toxins that cause a reduced bone marrow response to EPO, systemic inflammation conditions, and vitamin deficiencies are some of the underlying mechanisms of anemia in CKD." (PMID 37374094, 2023). "Impaired glomerular filtration rate might be associated to anemia due to decreasing erythropoietin synthesis by the kidney." (PMID 37652948, 2023). "Furthermore, blunted erythropoietin response led by splanchnic autonomic denervation is associated with developing anemia among patients with diabetic neuropathy." (PMID 37163539, 2023). "Anemia of prematurity is caused by premature birth which occurs before placental iron transport and fetal erythropoiesis completion; low plasma levels of erythropoietin due to reduced production and accelerated catabolism; and iatrogenic blood loss caused by laboratory testing." (PMID 37685781, 2023). "Decreased GFR leads to anemia due to impaired erythropoietin production and other causes." (PMID 37840949, 2023). "Dialysis patients are more prone to blood loss and anemia necessitating blood transfusions due to multiple factors, including preoperative anemia of chronic disease, low erythropoietin levels, and a higher perioperative bleeding risk due to the uremic effect on platelets." (PMID 37533126, 2023). "Insufficient EPO production caused by hyperglycemia may be the main reason for early anemia in diabetic patients." (PMID 37430329, 2023). "Thus, iron supplementation, especially in combination with erythropoietin is recommended when the anaemia of chronic disease is accompanied by iron deficiency with complete depletion of iron stores." (PMID 37005650, 2023). "Interestingly, all the malaria-infected pregnant women with serum anti-EPO antibodies in this study were anaemic, signifying the antibodies’ association with P. falciparum malaria-related anaemia in pregnancy." (PMID 36989322, 2023). "An absolute and/or relative deficiency of iron and/or erythropoietin, alterations in the red blood cells volume, haemodilution, and other mechanisms might impact the occurrence of anaemia in patients with HF." (PMID 36979951, 2023). "Management of anemia caused by CKD was the most frequent indication of EPO in the study population." (PMID 38029231, 2023). "Patients with renal insufficiency may experience varying degrees of anemia that could be linked to reduced production of endogenous erythropoietin (EPO) and iron deficiency." (PMID 37199588, 2023).